PRX (periaxin)
Diseases named in the same sentence as PRX in open-access papers:
PRX is named in the same sentence as 48 diseases in open-access papers, as found by Europe PMC text mining. Sharing a sentence is not in itself a finding about the gene and the disease. The quoted sentences say what the papers report.
neuropathy (8 papers, 2014 to 2023). A disorder affecting the nervous system that manifests with pain, tingling, numbness, and/or muscle weakness. "Most of them are nonsense or frameshift mutations, suggesting that a loss of function is the pathogenic mechanism for PRX-related neuropathies." (PMID 37470010, 2023). "Although the association of Periaxin mutations was confirmed in autosomal recessive CMT4F neuropathy, DRP2 null mice showed weak myelin abnormality." (PMID 31217940, 2019). "O-GlcNAc mapping of proteins in sciatic nerve tissue identified among 122 others a myelin protein called periaxin (PRX) which is known in humans to be associated with neuropathy." (PMID 29790000, 2018). "Based on its localization to the Cajal bands of Schwann cells and the dymyelinating neuropathy phenotype associated with the gene knockout mouse model,periaxin has been confirmed to play an essential role in stabilization of the Schwann cell-axon unit." (PMID 24633211, 2014). "Notably, the periaxin-deficient mouse model of the neuropathy Charcot-Marie-Tooth 4F displays a highly pathological myelin proteome profile, exemplified by the discovery of reduced levels of the monocarboxylate transporter MCT1/SLC16A1 as a novel facet of the neuropathology." (PMID 32130108, 2020).
Charcot-Marie-Tooth disease (5 papers, 2012 to 2022). An inherited degenerative disorder involving the peripheral nerves. "Several loss-of-function mutations in periaxin have been described and linked to autosomal recessive Dejerine Sottas neuropathy and to demyelinating Charcot-Marie-Tooth disease." (PMID 24633211, 2014). "Furthermore, PRX mutations result in various demyelinating peripheral neuropathies, such as Charcot-Marie-Tooth (CMT) disease and Dejerne-Sottas disease, again reflecting PRX’s major role in the myelination of peripheral nerves." (PMID 35158796, 2022). "Some forms of Charcot-Marie-Tooth disease (CMT) are due to mutations in myelin proteins and can manifest prominent sensory involvement, for instance, CMT4F, which is caused by mutations in the periaxin gene." (PMID 22704856, 2012).
breast carcinoma (3 papers, 2016 to 2025). "We found that ANXA2R protects against in situ breast cancer by reducing the expression of cathepsin F. PRX and CRY2 are protective factors for both cathepsin Z and in situ breast cancer." (PMID 39944834, 2025).
Dejerin-Sottas disease (3 papers, 2013 to 2023). "In humans, nonsense mutations in periaxin cause an autosomal recessive form of CMT4F (Dejerin-Sottas disease), which is one of the severe hereditary motor and sensory neuropathies." (PMID 23586671, 2013). "Dejerine-Sottas neuropathy and Charcot-Marie-Tooth type 4F (CMT4F) are the two different clinical phenotypes observed in association with PRX gene mutation." (PMID 31523542, 2019).
Charcot-Marie-Tooth disease type 4F (2 papers, 2023). "Mutations in PRX can lead to Charcot-Marie-Tooth disease type 4F (CMT4F)." (PMID 37470010, 2023).
demyelinating peripheral neuropathy (2 papers, 2018 to 2019). "Mutations that truncate periaxin from the C terminus cause demyelinating peripheral neuropathy, Charcot-Marie-Tooth (CMT) disease type 4F, indicating a function for the periaxin C-terminal region in myelination." (PMID 31024253, 2019). "In addition, loss of function PRX mutations in humans cause a demyelinating peripheral neuropathy, but there are no symptoms that can be attributed to impaired cerebral endothelial function reported in affected individuals." (PMID 29968755, 2018).
demyelination (2 papers, 2015 to 2018). "A single cobra venom injection, and in periaxin-deficient mice, the dephosphorylation of neurofilaments, resulte in paranodal demyelination associated with painful behaviors." (PMID 25739080, 2015). "In a mouse model of CMT4F, complete loss of Periaxin first prevents normal Schwann cell elongation resulting in abnormally short internodal distances which can reduce nerve conduction velocity, and subsequently precipitates demyelination." (PMID 29623298, 2018).
injury (2 papers, 2025). Damage inflicted on the body as the direct or indirect result of an external force, with or without disruption of structural continuity. "Our findings highlight the therapeutic potential of combining an advanced NET-degrading agent, specifically PRX-119 with toxin-neutralizing antibodies as an effective strategy to attenuate acute lung injury and improve clinical outcomes." (PMID 41023796, 2025). "Altogether, these heatmaps indicate that PRx could aid in refining the ICP and CPP targets to alleviate the burden of secondary brain injury." (PMID 40343533, 2025).
lung carcinoma (2 papers, 2006 to 2023). "MUC16, PRX, and SDHA showed the highest frequency of deleterious mutations, occurring in all primary lung cancers and BMs (Case 2, Case 3, Case 5, and Case 7)." (PMID 37384291, 2023). "In this study, we found that MUC16, PRX, and SDHA showed a high frequency of deleterious mutations in all primary lung cancers, and BMs inherited the genomic variations, which indicated those genes may act as lung cancer cell dissemination driver genes." (PMID 37384291, 2023). "Prior studies of PRX expression showed that PRXI, II, III, V and VI are highly over-expressed in the human lung cancer cells." (PMID 17020618, 2006).
sensory ataxia (2 papers, 2024 to 2025). Any ataxia in which the causes of the disease is a perturbation of the sensory system, leading to its dysfunction. "Patients with pathogenic PRX variants showed prominent sensory ataxia." (PMID 39776111, 2025).
Age-related cataract (1 paper, 2025). A type of cataract (opacification of the lens) that forms during the course of aging. "Periaxin variants and Cx46 knockout disrupt lens fiber cell homeostasis and cytoskeletal organization, contributing to the severity of age-related cataracts." (PMID 40993206, 2025).
bronchiectasis (1 paper, 2016). Segmental, irreversible dilation of the bronchial tree resulting in the accumulation of secretions which leads to obstruction. "Of the remaining variants only two were located within genes functionally related to the phenotype under study; these were periaxin (PRX) for the peripheral neuropathy and Interleukin-33 (IL33) for the bronchiectasis." (PMID 26059842, 2016).
Cerebral ischemia (1 paper, 2021). Restriction of arterial blood supply to the brain associated with insufficient oxygenation to support the metabolic requirements of the tissue. "In addition, although pharmacological research on PRX and 3-MPR is relatively rare, PRX showed great potential in suppressing tumor growth as a prodrug, and 3-MPR exhibited protective effects on cerebral ischemia-reperfusion injuries." (PMID 33572490, 2021).
chronic inflammatory demyelinating polyradiculoneuropathy (1 paper, 2025). A rare neurological disorder in which there is inflammation of nerve roots and peripheral nerves and destruction of the fatty protective covering (myelin sheath) over the nerves. "Peripherin and periaxin, biomarkers of peripheral nerve axonal damage and acute demyelination, respectively, have recently been validated in the inflammatory neuropathies Guillain‐Barré syndrome (GBS) and chronic inflammatory demyelinating polyradiculoneuropathy (CIDP)." (PMID 40542608, 2025). "Peripherin and periaxin, biomarkers of peripheral axonal damage and demyelination, respectively, have recently been validated in Guillain‐Barré syndrome (GBS) and chronic inflammatory demyelinating polyradiculoneuropathy (CIDP)." (PMID 40542608, 2025).
congenital cataracts (1 paper, 2023). "Heterozygous mutations in PRX have been detected in pedigrees with congenital cataracts." (PMID 37470010, 2023).
diabetes mellitus (1 paper, 2024). A metabolic disorder characterized by abnormally high blood sugar levels due to diminished production of insulin or insulin resistance/desensitization. "Antibodies to PRX were previously found in the sera of patients with diabetes mellitus and monoclonal gammopathy of undetermined significance." (PMID 39669579, 2024).
Fabry disease (1 paper, 2023). Fabry disease (FD) is a progressive, inherited, multisystemic lysosomal storage disease characterized by specific neurological, cutaneous, renal, cardiovascular, cochleo-vestibular and cerebrovascular manifestations. "PEGylation was implemented in a new enzyme replacement therapy for Fabry disease (FD), pegunigalsidase-alfa (PRX-102)." (PMID 37818380, 2023).
glioma (1 paper, 2024). A benign or malignant brain and spinal cord tumor that arises from glial cells (astrocytes, oligodendrocytes, ependymal cells). "Furthermore, downregulation of PRX has been associated with better response to chemotherapy in glioma." (PMID 39766155, 2024).
ischemia (1 paper, 2018). A hypoperfusion of the BLOOD through an organ or tissue caused by a PATHOLOGIC CONSTRICTION or obstruction of its BLOOD VESSELS, or an absence of BLOOD CIRCULATION. "It remains possible that PRX plays a homeostatic role under perturbed states (e.g. during inflammatory challenges and ischemia)." (PMID 29968755, 2018).
malignant mesothelioma (1 paper, 2021). A malignant neoplasm of the pleura or peritoneum, arising from mesothelial cells. "Using cellular models of malignant mesothelioma, we show here that PRX3 expression and mROS levels in cells correlate with sensitivity to TS and that TS reacts selectively with PRX3 relative to other PRX isoforms." (PMID 33498547, 2021).
muscle atrophy (1 paper, 2023). The loss of muscle tissue due to inactivity or disease. "Clinically, deletion or mutation of the periaxin gene can cause the demyelinating CMT4F-associated muscle atrophy." (PMID 36870952, 2023). "Meanwhile, Ad-periaxin did not obviously alter the numbers of MyHC-I- and MyHC-II-positive fibers, indicating that gene therapy targeting L-periaxin in skeletal muscle alone could not be an effective treatment strategy for CMT4F-associated muscle atrophy." (PMID 36870952, 2023).
Parkinson disease (1 paper, 2021). A progressive degenerative disorder of the central nervous system characterized by loss of dopamine producing neurons in the substantia nigra and the presence of Lewy bodies in the substantia nigra and locus coeruleus. "We note that mutations in PRX have been previously shown to cause peripheral neuropathies, which are not uncommon in Parkinson’s disease and rheumatoid arthritis patients, but do not speculate on the relationship between these observations." (PMID 33771206, 2021).
scoliosis (1 paper, 2023). A congenital or acquired spinal deformity characterized by lateral curvature of the spine. "Although most were associated with classic demyelinating phenotypes (55/75, 73.3%), there was considerable phenotypic heterogeneity such as prominent deep sensory disturbances (SH3TC2, PRX) and scoliosis (SH3TC2, MPZ, and PMP22)." (PMID 37519884, 2023).
Sepsis (1 paper, 2025). Sepsis is defined as life-threatening organ dysfunction caused by a dysregulated host response to infection. "For this purpose, we selected PRX-119, a PEGylated recombinant human DNase I that exhibits extended half-life in the circulation and has previously shown efficacy in sepsis mouse model of NET-related disease." (PMID 41023796, 2025).
situ breast cancer (1 paper, 2025). "Cathepsin Z can mediate the effects of PRX, CRY2, ADCY3, and PELATON on in situ breast cancer." (PMID 39944834, 2025).
Stroke (1 paper, 2018). Sudden impairment of blood flow to a part of the brain due to occlusion or rupture of an artery to the brain. "Future studies, such as the generation of mice expressing human PRX and other human-only factors, will allow critical testing of the possibility that humanizing the cerebrovascular will advance the predictive value of mouse models of stroke and other brain blood vessel disorders." (PMID 29968755, 2018).
tumor (7 papers, 2017 to 2021). "DFT1 presents as large tumours around the face and oral cavity which are strongly positive for the myelin associated marker protein Periaxin (PRX)." (PMID 34780568, 2021). "Differential expression analysis of tumor and non-tumor host tissue identified Schwann cells as the likely origin of the cancer cell line and provided a diagnostic test using tumor staining with an antibody against periaxin (PRX), which is a Schwann cell-specific myelin protein." (PMID 30205843, 2018). "The tumor was immunonegative for CD3, CD20, PAX5, MUM1, pan-cytokeratin, S100, NSE, p75NTR, NeuN and periaxin." (PMID 34977226, 2021). "In 2014, grossly identical facial tumours were identified which have a distinct histology, which lacked expression of PRX." (PMID 34780568, 2021). "DFTD was confirmed on biopsy by periaxin expression and there were no signs of immune cell infiltration in the tumour." (PMID 28276463, 2017). "In addition, we identified that regulation of some of the tarGenes (e.g., PRX, HIPK2, and PPARD) may be important for tumor progression." (PMID 30424545, 2018).
infection (6 papers, 2011 to 2023). The state of being infected such as from the introduction of a foreign agent such as serum, vaccine, antigenic substance or organism. "The activity of these four biochemical markers was also evaluated in treated groups to evaluate any potential toxicity of Et-Bra (N versus N-PrX) and interference in the course of infection (Tc versus Tc-PrX)." (PMID 19213854, 2011). "However, four upregulated PRX genes were similar to peroxidase when combined with the results of high ROS content and more dead cells at the late stage of infection, which indicated that PRXs played an important role in ROS production." (PMID 37627262, 2023). "In contrast, SG3PDH/PRX-MAP combined with the type 2 cytokines, thymic stromal lymphopoietin (TSLP), IL-25, and IL-33, switched the antigen specific response elicited during a challenge infection towards a Th2 phenotype." (PMID 24465551, 2014). "Interestingly, examination of the lungs at 6 days after infection indicated that the combined vaccine of SmCB1 and SG3PDH/PRX-MAP elicited significant protection against the early migratory stages of the parasite." (PMID 24465551, 2014).
peripheral neuropathies (6 papers, 2015 to 2022). "Through this approach we were able to identify what we believe to be the causative variant (R1070*), in the gene PRX, for the peripheral neuropathy part of the phenotype displayed in this family." (PMID 26059842, 2016). "Through the use of whole-exome sequencing we were able to simplify this complex phenotype and identified a causative mutation (p.R1070*) in the gene periaxin (PRX), a gene previously shown to cause peripheral neuropathy (Dejerine–Sottas syndrome) when this mutation is present." (PMID 26059842, 2016).
cancer (5 papers, 2016 to 2021). A tumor composed of atypical neoplastic, often pleomorphic cells that invade other tissues. "The identification of DFT2 as a Schwann cell cancer was initially surprising due to the low expression of myelin-specific proteins such as periaxin by this cancer." (PMID 35055975, 2021). "After the discovery of a second facial cancer (DFT2), cytogenetics and the absence of periaxin expression confirmed the independence of the new cancer from DFT1 (the original DFTD)." (PMID 35055975, 2021). "However, immunohistochemistry alerted to something different, as the cancer cells did not express periaxin." (PMID 35055975, 2021). "The origins of TS specificity could come from a combination of many variables, including normal versus cancer cell ROS levels, PRX3 levels, differences in the cellular localization of TS and/or PRX enzymes and differences in the reactivity and structural features of the PRX proteins." (PMID 33498547, 2021).
genetic diseases (1 paper, 2017). "Some genetic diseases also lead to a reduced internodal length outcome: Periaxin and Laminin 2 (also called Merosin) mutations induce short myelin sheath internodes in peripheral nerves and lead to CMT4F and Lama2 neuromuscular disease respectively." (PMID 29354031, 2017).
neurodegenerative disease (1 paper, 2019). A disorder of the central nervous system characterized by gradual and progressive loss of neural tissue and neurologic function. "The PRX-β4 integrin complex is likely to be important in both normal myelination, myelin maintenance, as well as the pathophysiology of neurodegenerative disease." (PMID 31024253, 2019).
PRX also shares sentences with these, for which no sentence is quoted: Atrophy (1 paper); cataract (1); congenital muscular dystrophy (1); demyelinating disease (1); hereditary motor and sensory neuropathy (1); juvenile amyotrophic lateral sclerosis (1); liver fibrosis (1); mental retardation (1); monoclonal gammopathy of undetermined significance (1); neurofibromatosis (1); neuromuscular disease (1); nuclear cataract (1); rheumatoid arthritis (1); schizophrenia (1); spastic ataxia (1); velocardiofacial syndrome (1).